KRT20 (keratin 20)
Diseases named in the same sentence as KRT20 in open-access papers (continued):
Sharing a sentence is not in itself a finding about the gene and the disease.
Anal fistula (1 paper, 2015). An abnormal connection between the epithelialised surface of the anal canal and the perianal skin. "In immunohistochemical staining, both the rectal lesion and the anal fistula stained negative (−) with antibodies to cytokeratin 7 (CK7) and positive (+) with antibodies to cytokeratin 20 (CK20)." (PMID 26943447, 2015).
anal tumor (1 paper, 2019). "Immunohistochemistry revealed that both the rectal tumor and anal tumor were cytokeratin 7 (CK7) − and cytokeratin 20 (CK20) +." (PMID 31429762, 2019).
carcinoid tumor (1 paper, 2009). A slow growing neuroendocrine tumor, composed of uniform, round, or polygonal cells having monotonous, centrally located nuclei and small nucleoli, infrequent mitoses, and no necrosis. "The carcinoid tumor component was strongly positive for CD56, chromogranin and synaptophysin, weakly positive for pancytokeratin, and negative for carbonic anhydrase IX, CD99, CDX2, cytokeratin 7, cytokeratin 20 and smooth muscle actin." (PMID 19523243, 2009).
clear cell carcinoma (1 paper, 2008). "Diagnosis of clear cell carcinoma was based on certain histological characteristics of the tumour and immunohistochemical analysis (PAS staining, keratins AE1/AE3, EMA, cytokeratin 7, cytokeratin 20, melanosomes, vimentin, Chromogranin, Synaptophysin, S-100, SMA)." (PMID 18442419, 2008).
ductal adenocarcinomas (1 paper, 2015). "Most of the primary ductal adenocarcinomas of breast are immunoreactive to cytokeratin 7 (CK 7 (+)) and nonreactive to cytokeratin 20 (CK 20 (−))." (PMID 25883818, 2015).
enteritis (1 paper, 2025). Inflammation of the small intestine. "Our study demonstrated that enteritis-causing Salmonella infection resulted in diminished ISCs activity, as evidenced by the downregulation of Lgr5, PCNA, KRT20, and Villin expression." (PMID 40059168, 2025).
extrahepatic bile duct carcinoma (1 paper, 2012). A carcinoma that arises from epithelial cells of the extrahepatic bile duct. "Cytokeratin 7 (CK7) is almost always positive, Cytokeratin 20 (CK20) can be positive, more often in extrahepatic bile duct carcinoma than intrahepatic cholangiocarcinoma." (PMID 22284391, 2012).
head and neck squamous cell carcinoma (1 paper, 2025). A squamous cell carcinoma that arises from any of the following anatomic sites: lip and oral cavity, nasal cavity, paranasal sinuses, pharynx, larynx, and salivary glands. "Notably, KRT20 was identified as a key gene associated with lymphatic metastasis and poor prognosis in head and neck squamous cell carcinoma (HNSCC), with overexpression enhancing migration and invasion abilities of cancer cells." (PMID 40917881, 2025).
lymphoepithelioma (1 paper, 2022). "The tumor cells were positive for cluster of differentiation (CD) 10, cytokeratin (CK) AE1/AE3, cytokeratin 7, cytokeratin 20, cytokeratin 34βE12, GATA binding protein 3 (GATA3), and protein‐63 (p63), which are markers of lymphoepithelioma‐like carcinomas." (PMID 36052737, 2022).
metastatic tumors (1 paper, 2022). "A recent study showed that the CK7 (KRT7), CK20 (KRT20), and SATB2 immunohistochemical markers could assist in differentiating primary MCs from metastatic tumors." (PMID 36818673, 2022).
neuropathy (1 paper, 2024). A disorder affecting the nervous system that manifests with pain, tingling, numbness, and/or muscle weakness. "A previous study showed an absence of cytokeratin 20 in neuropathic bladders, and the possible reason for this might be the impairment of normal voiding function in neuropathy patients, further affecting the expression of differentiation markers like K20." (PMID 38668463, 2024).
oral squamous cell carcinoma (1 paper, 1999). "We examined the expression of cytokeratin 20 (CK20) mRNA in the peripheral blood of oral squamous cell carcinoma (SCC) patients by reverse transcriptase polymerase chain reaction (RT-PCR)." (PMID 10408852, 1999).
Pleural effusion (1 paper, 2019). The presence of an excessive amount of fluid in the pleural cavity. "Malignant cells in the pleural effusion were positive for Cytokeratin 7 (CK7) and negative for cytokeratin 20 (CK20)." (PMID 30634950, 2019).
pseudomyxoma peritonei (1 paper, 2022). An appendix cancer that is characterized by progressive accumulation of mucus-secreting tumor cells within the abdomen and pelvis. "Ultrasound-guided percutaneous biopsy of an abdominal wall lesion was executed and histopathological examination identified localization of pseudomyxoma peritonei, with immunohistochemical staining being positive for cytokeratin 20 (CK-20) and CDX-2 and negative for cytokeratin 7 (CK-7)." (PMID 35538541, 2022).
rectum adenocarcinoma (1 paper, 2023). An adenocarcinoma arising from the rectum. "Consistently, in our study, enhanced expression of KRT20 was found in colon and rectum adenocarcinoma." (PMID 36949761, 2023).
sarcomatoid carcinoma (1 paper, 2018). A malignant epithelial neoplasm characterized by the presence of spindle cells and anaplastic morphologic features. "As other immunohistochemical markers were negative, including CD45, CD163, CD68, Desmin, Myogenin, Melanoma, S100, α-SMA, Cytokeratin 7, Cytokeratin 20, MDM2 and CDK4, the tumors were diagnosed as sarcomatoid carcinomas." (PMID 29874846, 2018).
Sepsis (1 paper, 2024). Sepsis is defined as life-threatening organ dysfunction caused by a dysregulated host response to infection. "We established a prognostic model consisting of four sepsis-related genes: KRT20, PAEP, CCR3, and ANLN." (PMID 39421149, 2024).
small intestinal cancer (1 paper, 2024). "Histopathology and immunohistochemistry of the uterine tumor revealed that it was a metastasis of small intestinal cancer (Cytokeratin 7 [CK7] [−], Cytokeratin 20 [CK20] [+], Special AT-Rich Sequence-Binding Protein 2 [SATB2] [+], Paired Box Gene 2 [PAX2] [−], and estrogen receptor [ER] [−])." (PMID 39156866, 2024).
urachal adenocarcinomas (1 paper, 2025). "Moreover, cytokeratin 20 (CK20) is expressed in nearly 100% of urachal adenocarcinomas and is frequently accompanied by CDX2 positivity, serving as a crucial immunophenotypic marker for distinguishing enteric from non-enteric adenocarcinomas and clarifying tumor origin." (PMID 41323974, 2025).
tumor (179 papers, 1999 to 2026). "Tumours with an elevated expression of markers associated with luminal differentiation (KRT20, ERBB2, ESR1) were associated with a higher chance of pCR (55% vs. 15.8%, p = 0.009)." (PMID 34073233, 2021). "High KRT20 expression in lymph nodes after radical cystectomy is associated with a higher tumor stage, a higher rate of micrometastasis, and a worse outcome." (PMID 30380731, 2018). "One of the study results revealed that positivity of Cytokeratin 20 associated with increasing tumor grade and stage and it was observed that 69.4% cases of high grade tumors showed Cytokeratin 20 positivity as compared to 45.00% of other grades of tumours." (PMID 26640315, 2015). "The neoplasm metastasis associated genes KRT20, tumor protein D52 (TPD52), MUC1, and KIT are upregulated in the poor prognosis tumors while homeobox B1 (HOXB1) is downregulated." (PMID 24634783, 2014). "Additionally, in the past, several studies demonstrated the association between high KRT20 expression and high tumor stage and grade." (PMID 30380731, 2018). "And also KRT20, typically associated with luminal tumours, showed a lower expression in this group." (PMID 30258198, 2018). "In addition to cytomorphological analysis, gene expression of tumor associated genes (Cytokeratin-18, Cytokeratin-19, Cytokeratin-20, Cytokeratin-7, EPCAM, MUC1, HER2, EGFR) and of leukocyte markers (e.g. CD45, CD68) was tested in enriched CTC fractions." (PMID 25862542, 2016). "They found cytokeratin 20 positivity was associated with increasing tumor grade and stage." (PMID 25089155, 2014). "Immunohistochemistry showed that cytokeratin 20 was partially positive and caudal type homeobox 2 was positive in approximately 50% of the tumor cells." (PMID 41630024, 2026). "FKBP9L and CCDC108 were found to be significantly increased in tumor tissues, whereas the expression of KRT20, ZFAND2A, and SIRT3 was significantly decreased in tumors." (PMID 40406545, 2025). "Bladder cancer 4 (BLCA-4), minichromosomal maintenance 5 (MCM5), human telomerase reverse transcriptase (hTERT), circulating tumor cells (CTCs), and cytokeratin 20 (CK-20) have been reported to be biomarkers of urothelial carcinoma." (PMID 39273579, 2024). "Rainbow tracing also validates that Lgr5+ tumor cells produce Lgr5+ cells and keratin 20 (KRT20)-positive mature cells, and thus have the ability to self-renew and differentiate, conferring Lgr5 as a marker of colorectal CSCs." (PMID 39872442, 2024). "This study concluded that basal tumours with KRT5/6, p63, and KRT14 expression had a better response to chemotherapy, while luminal tumours with active PPAR expression and activating mutations in FGFR3 showed expression of KRT20, FOXA1, and GATA3." (PMID 39594166, 2024). "To investigate the mechanisms orchestrating cancer stemness and tumour development, we analysed the transcriptional differences between differentiated (Krt20+Apoc2+Fabp2+) and stem (Lgr5+Cd44+Sox9+) cancer cells within tumours." (PMID 38658753, 2024). "Luminal tumours, accounting for about 50% of MIBCs, present high expression of urothelial differentiation markers (GATA3, FOXA1, KRT20, uroplakins) and are enriched in activating mutations of FGFR3." (PMID 36944729, 2023). "Knockout of LGR5 + cells leads to transient tumour regression, but KRT20 + tumour cells quickly differentiate into LGR5 + tumour cells." (PMID 37537666, 2023). "Strikingly, expression of ATOH1 and KRT20 varied in intensity and positivity within individual tumor sections, indicating the potential for heterogenous subpopulations." (PMID 36719743, 2023). "Class 3 tumours show some of the gene expression characteristics associated with MIBC (KRT5+, KRT14+, CD44+, KRT20− and PPARG−)." (PMID 36928373, 2023). "The detection of cytokeratin 7 (CK7) and cytokeratin 20 (CK20) also contributes to tumor identification." (PMID 36966290, 2023).
tumor (continued). "Immunohistochemical staining showed the tumour cells were diffusely positive for cytokeratin 20 (CK20) and caudal-related homeobox transcription factor 2 (CDX2) while cytokeratin 7 (CK7), Wilms tumour 1 (WT1) and tumour protein 63 (p63) were all negative." (PMID 37032350, 2023). "Surprisingly, stem cell markers and associated WNT signaling genes, including Lgr5, decreased in tumor cells along the treatment timeline in a gradient-like manner; this corresponded with increase in differentiated epithelial genes Krt20 and Krt8." (PMID 35600339, 2022). "Primary CRCs and macrometastases exhibited similar distribution of cell populations, including proliferative cells, Lgr5+ ISC-like cells, Krt20+ differentiated tumor cells and HRCs, most of which were also Krt20+." (PMID 36352230, 2022). "IHC staining for the differentiation marker KRT20 revealed a significant reduction of positive staining in both the normal colonic mucosa as well as in tumours arising in Ehf KO;Cdx1KO mice compared to WT mice or mice lacking either factor alone." (PMID 35606410, 2022). "As reported by some studies, one marker showing promise in this area is the expression of Cytokeratin 20 (CK20) by the tumor cells." (PMID 36540439, 2022). "The stromal-rich tumor subgroup had low pCR (1/9; 12.5%), with the only exception in the stromal cluster having again high KRT20 and low FGFR1 expression, indicating the limitation of the cluster method." (PMID 35887247, 2022). "Fitting the scRNAseq analyses, we identified two Emp1-TOM+ subsets; one expressed KRT20 and was located mainly in the tumor cores, whereas the other was positioned at invasion fronts, lacked KRT20 and expressed the highest levels of TOM reporter." (PMID 36352230, 2022). "Epithelial-associated genes KRT20 and BMP7 were consistenantly upregulated in all blood samples as compared to tumours." (PMID 35493092, 2022). "The tumor displayed a strong activation of genes for mesodermal (Desmin, Myog, Myh1 and Myh3) and endodermal (Afp, Krt20) tissue differentiation." (PMID 33468253, 2021). "This research agrees with previous reports that found KRT20 overexpression to be an important biomarker of tumor recurrence, in comparison with lower expression levels in the normal urothelium." (PMID 34771699, 2021). "In univariable Cox regression analysis, positive nodal status, tumor stage, and expression of FOXA1 and KRT20 were associated with worse outcome." (PMID 32252315, 2020). "Several epithelial markers were elevated in RE, Keratin 13, Keratin 20, and Gastrokine-1, relative to other groups, while neoplasia markers desmin and vimentin were elevated in BE and EAC compared to control." (PMID 32650561, 2020). "Among the top downregulated ones we found keratin 6A and keratin 20 (KRT6A and KRT20) suggestive of the reduction of tumor cells as the result of TCB-mediated killing." (PMID 33330050, 2020). "Immunohistochemical analysis showed the tumor tested positive for Cytokeratin 20 (CK20) and Cytokeratin 7 (CK7) that are distributed in epithelia and their neoplasms." (PMID 32832071, 2019). "In contrast, NMIBC with high KRT20 mRNA expression was accompanied by significantly increased rates of tumor progression." (PMID 30380731, 2018). "Downregulation during tumorigenesis is a recognized weakness of using differentiation markers such as KRT20 as markers of tumor metastasis." (PMID 29415677, 2018). "Next, we investigated the relationship between relative mRNA levels and the tumour‐cell expression of the terminal differentiation markers KRT20 and UPK3." (PMID 28195647, 2017). "Immunohistochemical examination of this tumor revealed positive staining for Cytokeratin 20, Mucin 2, and CDX2, although Cytokeratin 7 and Mucin 6 were negative." (PMID 28503335, 2017). "In our study, cultures derived from tumours with varying expression of cytokeratin 20 or CEA, also demonstrated variation in expression for individual spheroids." (PMID 28877221, 2017).
tumor (continued). "Among the most conspicuous of these observations was the stochastic appearance of tumour‐cell KRT20 staining, and, even more, the aberrant subcellular localization of these markers." (PMID 28195647, 2017). "Comparison of spheroids with the original tumour revealed that spheroid culture generally preserved adenocarcinoma histology and expression patterns of cytokeratin 20 and carcinoembryonic antigen." (PMID 28877221, 2017). "Immunostaining revealed that cytokeratin 20 was expressed to a varying degree by spheroid cultures established from different tumours." (PMID 28877221, 2017). "Immunostaining showed the tumor to be cytokeratin 20 (CK20)-positive with a typical paranuclear dotlike staining pattern." (PMID 27814751, 2016). "We observed that treatment with tumor DNA also results in overexpression of cytokeratin 20, and E-cadherin which was validated both at the RNA and the protein level." (PMID 26133168, 2015). "The tumor cells are diffusely and strongly positive for cytokeratin 20, villin, and focally positive for CDX2, CA19-9, and CK7." (PMID 24891967, 2014). "In this case, the tumor cells were positive for cytokeratin 20 and CD56, which demonstrated both epithelial and neuroendocrine features." (PMID 24073348, 2013). "Our recent work has shown the feasibility of using a refined immunomagnetic enrichment (IE) assay to detect cytokeratin 20-positive circulating tumour cells (CK20 pCTCs) in colorectal cancer (CRC) patients." (PMID 21364588, 2011). "The tumor tissue immunohistochemical study proved positive for cytokeratin 20(CK20), neuronal specific enolase (NSE) and cytokeratin CAM5.2." (PMID 21609425, 2011). "Some MCC tumor sections were co-stained with antibody to cytokeratin-20 (CK20, a histological marker of MCC tumor cells) instead of CM2B4." (PMID 19750217, 2009). "Immunohistochemically, tumor cells were positive diffusely for Cytokeratin 7, and focally for Cytokeratin 20 and Thyroid Transcription Factor-1." (PMID 18823534, 2008). "A lung primary was unlikely as the tumour was characterized by positivity for cytokeratin 20 and negativity for the thyroid transcription factor-1 protein (TTF-1) in immunohistochemistry." (PMID 18667060, 2008). "The reverse transcription polymerase chain reaction (RT-PCR) amplification of cytokeratin 20 (CK20) mRNA is considered a promising candidate method for the detection of circulating tumour cells in bone marrow and peripheral blood of cancer patients." (PMID 10555760, 1999). "Regarding the expression of luminal and basal biomarkers, Layer3.1 tumor presented higher expression of KRT20, a luminal-papillary biomarker, whereas Layer3.2 had higher expression of KRT5, KRT6a, KRT14, and CD44 basal biomarkers, but also PGM5, DES, and SGCD luminal-infiltrated biomarkers." (PMID 41516353, 2026). "Provided immunohistochemical stains showed strong pancytokeratin expression coupled with perinuclear dot‐like staining for cytokeratin 20 in a distinct regional distribution, predominantly in areas where the tumor cells formed cohesive nests and cords within sclerotic stroma." (PMID 40640075, 2025). "Similarly, the elimination of Lgr5+ CSCs with iCaspase 9 and Dimerizer triggers a shrinkage of tumor volume, accompanied by activation of KRT20+ differentiated cells and a large number of Lgr5− cells dedifferentiate into colonies." (PMID 39872442, 2024). "Thus, different pathological tests need to be performed to evaluate or demonstrate that propolis also reduces the size of colonic neoplastic lesions through the expression of common tumor markers, such as KRT20." (PMID 37960147, 2023). "Further, the expression of the proliferation marker Ki67, Keratin 20 (KRT20) as a marker of differentiated tumor cells, or nuclear β-catenin that reports WNT signaling activity, highlights cellular heterogeneity with varying degrees of differentiation within the tumors." (PMID 36077793, 2022). "Tumor cells of cluster 3 upregulated the differentiation marker Krt20." (PMID 36352230, 2022).